CD68 (CD68 molecule)
Diseases named in the same sentence as CD68 in open-access papers (continued):
Sharing a sentence is not in itself a finding about the gene and the disease.
glioma (continued). "The expression of CD68 antigen has been assessed in glioma tissues around areas where necrosis and foamy cells were absent, since both of the elements could represent a possible cause of inaccurate interpretation." (PMID 29584702, 2018). "CD68 was also shown to be significantly existed in glioma tissues versus paired normal controls." (PMID 27765933, 2016). "Confocal analyses of the co-staining showed that in addition to glioma cells, high RTK signaling activities were detected in vessel cells and infiltrating TAMs in RMPAhigh gliomas; weak or barely detectable p-AKT activity in CD68+ or CD31+ cells was observed in RMPAlow gliomas." (PMID 27385209, 2016). "Moreover, in the untreated and Plerixafor-treated tumors we detected more CD11b+/CD68+ cells respect to peptide R-treated gliomas, suggesting that peptide R treatment perturbs the activation state of GAMs." (PMID 27015814, 2016). "In this regard, tumour-infiltrating M/Mφ have lower CD68 expression in EE mice as compared to SE mice, suggestive of changes in their phenotype, and this is accompanied by reduced glioma cell proliferation and invasion into surrounding parenchyma, and reduced astrogliosis." (PMID 25818172, 2015). "Finally, sections of glioma tissue obtained from surgical resection of patients diagnosed with IV grade glioblastoma (GBM) were stained for CD68 (PG-M1 clone), a marker of phagocytic activity of macrophages/microglia." (PMID 24689533, 2014). "Interestingly, in human glioma tissue obtained from surgical resection of patients with IV grade glioblastoma, we detected a significant amount of CD68 positive cells." (PMID 24689533, 2014). "In contrast, CD68+ monocyte-derived cells and CD11c+CD68+ cells were more frequent at the infiltrating edge (P = 0.0164 and P = 0.0052, respectively) as well as within the tumor area (P = 0.0029 and P = 0.0007, respectively) of glioma specimens relative to brain metastases." (PMID 35316217, 2022). "However, most glioma cases showed CD68+ macrophage/microglia and CD163+ TAM infiltration." (PMID 32528967, 2020). "CD163 expression alone is also a potential biomarker for diagnosis of glioma patients (AUC = 0.7565, Appendix Figure A2C ), whereas neither CD68 nor iNOS expression exhibits the diagnostic accuracy (CD68, AUC = 0.5851; iNOS, AUC = 0.6013) (Appendix Figure A2A,B)." (PMID 32349342, 2020). "To explore the molecules that influence prognosis, we further mining the survival data from the public databases about SERPINA3, CD68 and IBA1 for glioma patients." (PMID 41550507, 2026). "We also confirmed through immunofluorescence staining that the expression of CD68 and IBA1 is higher in GBM specimens than in low-grade gliomas." (PMID 41550507, 2026). "Further, we examined the relation of SERPINA3 and these molecules in WHO II, III and IV gliomas form CGGA datasets and the mRNA level of SERPINA3 showed a positive correlation with CD68." (PMID 41550507, 2026). "Analyzing CGGA data, we observed a positive correlation between SERPINA3 mRNA expression and the levels of CD68 and IBA1 mRNA in primary gliomas, suggesting a link between SERPINA3 and GAM markers." (PMID 41550507, 2026). "The data demonstrated that co-expression of CD68/SERPINA3 and IBA1/SERPINA3 in glioma specimens, indicating SERPINA3 expression in GAMs." (PMID 41550507, 2026). "High levels of CD68 and IBA1 mRNA have shorter survival time compared with low levels in glioma patients." (PMID 41550507, 2026). "Our data confirmed that CD68 and IBA1 expression in WHO IV glioma were significantly enhanced compared with other WHO grade gliomas." (PMID 41550507, 2026). "Subsequently, to determine the localization of bacteria in glioma tissue, we quantified the cells co-expressing GFAP and LPS, as well as CD68 and LPS, using multicolor immunofluorescence staining on tissue sections." (PMID 39660865, 2025).
glioma (continued). "The results showed a significant increase in the number of infiltrating leukocytes (CD45+), macrophages (CD68+), and T lymphocytes (CD8+) in IDH wt gliomas compared to IDH mut gliomas." (PMID 39744679, 2025). "Our findings demonstrated that PDPN is notably correlated with the expression of CD68 and CD163 in glioma tissues." (PMID 38470096, 2024). "According to the Ivy Glioblastoma Atlas Project, MAP2K3, CD68 and CD276 were found to be upregulated in human glioma samples in the Perinecrotic zone (CTpnz) region of expression." (PMID 38938778, 2024). "Multiplexed fluorescence immunohistochemistry staining of PDPN, GFAP, CD68, and CD163 were performed in glioma tissue microarray." (PMID 38470096, 2024). "To further elucidate the biological importance of HEC1, we performed multiplex fluorescent immunofluorescence staining of macrophage marker CD68, CD163, along with glioma cell marker Glial fibrillary acidic protein (GFPA), across different grade of glioma." (PMID 39021287, 2024). "We observed that significant upregulation of mRNA expression levels for three TAM markers, MSR1/CD204, CD86, and CD68, suggested that TGFB2 is pivotal in establishing a pro-tumorigenic TME in gliomas mediated through TAMs." (PMID 38539537, 2024). "Iba1+ and CD16+ cells prevail in human low-grade gliomas, whereas CD68+ and CD163+ cells increase in high-grade gliomas, with a significant correlation between patients’ worsening overall survival." (PMID 38671983, 2024). "In addition, PDPN and TIMP1 were found to be highly expressed in high-grade glioma via The Human Protein Atlas database, and both correlated with m6A and macrophage marker CD68 in glioma tissue samples, which may serve as potential biomarkers for glioma prognosis." (PMID 38071304, 2023). "PTX3 is an important component of the GBM microenvironment that is produced by both tumor cells and infiltrating CD68‐positive macrophages, and local PTX3 levels correlate with glioma grade and malignancy." (PMID 37063077, 2023). "An interesting future experiment to further determine the expression patterns in different cell types of glioma tissue would be double fluorescence staining with BRMS1 and cell-type-specific markers, such as IDH1R132H, NeuN, GFAP, or CD68." (PMID 37296870, 2023). "Several researchers have observed an increase in M2 macrophages, marked by CD68 and CD163 expression, in high-grade gliomas." (PMID 37046685, 2023). "Our in vitro glioma IHC analysis also confirmed the riskscore positively correlated with IBA1, TMEM119, CD68, CSF1R, and TGFB1 protein expression." (PMID 35985661, 2022). "αDC1s had increased IL-12 secretion, and vaccination of αDC1s pulsed with glioma Ags resulted in intensive infiltration of CD8+ T cells and CD68+ macrophages in the glioma region of patients." (PMID 35806328, 2022). "CD68+p-STAT3+ (P = 0.0306) and CD163+p-STAT3+ (P = 0.0165) cells were significantly enriched in regions of necrosis in gliomas and brain metastases, respectively." (PMID 35316217, 2022). "The quantity of CD8+ cells at the distance of 0–25 μm and 25–50 μm neighboring SOX10-expressed cells exploded in the Glioma WHO IV group, while the amount of CD68+CD163+ cells also increased." (PMID 36524115, 2022). "High-grade gliomas had stronger EDEM2 expression based on immunohistochemistry, and the expression of cluster of differentiation 68 (CD68), cluster of differentiation 4 (CD4), and cluster of differentiation 8 (CD8) was higher in the samples." (PMID 36727065, 2022). "We performed multiplex immunofluorescence in the controlled group and different grades of glioma groups to further characterize the relationship between SOX10-expressed cells and neighboring CD68+CD163+ cells, and CD8+ cells." (PMID 36524115, 2022). "Intratumoral CD68+ (P = 0.0029), CD11c+CD68+ (P = 0.0018) and CD11c+CD68+CD163+ (P = 0.0029) cells were more likely to express p-STAT3 in gliomas." (PMID 35316217, 2022).
glioma (continued). "Immunohistochemistry staining for the M2 macrophage marker CD68 and CD163, mast cell marker CD117, neutrophil marker CD66b, and RNA sequencing of glioma samples from the XYNS cohort were performed." (PMID 34489938, 2021). "The immunostaining score evaluated by two professional pathologists showed that SPON2, IFI44, CD68, and CD206 were significantly overexpressed in high-grade gliomas." (PMID 34136486, 2021). "A co-expression of glioma biomarkers (GFAP, IDH1R132H, and PDGFRA) and macrophage biomarkers (CD68 and CD14) is also noticed on some cells, defined as GAM-GBM hybrid cells." (PMID 34071306, 2021). "What’s more, double-staining with antibodies against macrophage marker (CD68) and CPVL proved that the macrophage cell in glioma contributes to the CPVL expression." (PMID 34784299, 2021). "Lower levels of tumor-infiltrating macrophages, including CD68+ (~30%), F4/80+ (~50%), and CD11c+ macrophages (~50%), were identified in FUCA1-downregulated glioma tissues, and CCL2/CCL5 neutralizing Abs blocked this effect." (PMID 34071306, 2021). "Similar to gliomas, LMD in melanoma patients appears to demonstrate an enrichment of innate immune cells like CD68+ single cells (monocyte-derived cells) and CD163+ single cells or macrophages." (PMID 34691054, 2021). "Consistently, we found that high CD68 and VIM expression correlate with poor prognosis of glioma patients." (PMID 34805184, 2021). "JWH133 treatment also significantly increased the mRNA level of M2 subtype markers CD206, Arg1, and Ym1 and decreased the mRNA level of M1 subtype markers CD68, CD86, and iNOS in the tissues around glioma, in vivo (*P < 0.05 and **P < 0.01 vs. Vehicle)." (PMID 33330047, 2020). "Quantification of immune cells (CD20+ B cells, CD4+ T cells, CD8+T cells, CD68+ Macrophages, and CD163+ TAMs) in our 304 glioma cases (WHO I–IV)." (PMID 32528967, 2020). "VAP-1 and TAM biomarkers (CD68, iNOS, and CD163) were evaluated by immunohistochemistry in 108 gliomas from Kaohsiung Medical University Hospital." (PMID 32349342, 2020). "Several molecules have been reported as specific markers of TAMs in glioma, including CD204, CD163, CD11b, CD14, and CD68." (PMID 31140757, 2019). "Previous studies have demonstrated that activated macrophages in glioma tissue express high levels of CD163, CD68, CD206, and CD204." (PMID 28076333, 2017). "While tumor cells in glioma consistently express ZEB1, we observed mutually exclusive staining with markers of immune cells (CD45, CD68, Iba1, HLA-DR)." (PMID 28945795, 2017). "In contrast to our prior findings with CD68 and IBA1, we found a positive correlation between the percent of F11R+ cells and high-grade glioma (p<0.0001)." (PMID 24147027, 2013). "In glioma, the proportions of CD163+ macrophages among CD68+ macrophages, which would reflect the proportion of macrophages polarized to the M2 phenotype, were reported to be associated with histologic grade." (PMID 23555776, 2013). "Further the level of SERPINA3, CD68 and IBA1 with prognosis are detected in glioma patients." (PMID 41550507, 2026). "In addition, we further mining the survival time of CD68 and IBA1 mRNA in glioma patients from the CGGA databases." (PMID 41550507, 2026). "Moreover, we found that CD68 and IBA1 mRNA levels in WHO III and IV gliomas were higher than that of WHO II." (PMID 41550507, 2026). "Furthermore, we observed a strong correlation between high levels of SERPINA3, CD68, and IBA1 with reduced survival in patients with primary gliomas." (PMID 41550507, 2026). "Given that SERPINA3 levels were positively correlated with the expression of CD68 and IBA1 in CGGA databases, suggests that SERPINA3 may involve in forming glioma immunosuppression." (PMID 41550507, 2026).
glioma (continued). "Multiplex fluorescent immunofluorescence of human glioma tissue further showed positive correlation of HEC1 expression in glioma with the infiltration of M2 macrophages (CD68+CD163+), the malignant degrees of gliomas, and a lower survival probability of patients with high HEC1 expression." (PMID 39021287, 2024). "Combined, these data indicate that neither fractionated radiation nor KCa3.1 targeting with TRAM-34 nor their combination, induced pronounced changes in the abundance of Iba1+ or CD68+ reactive microglia and CD3+, CD8+ cytotoxic or FoxP3+ regulatory T cells in the SMA-560 VM/Dk glioma model." (PMID 37996600, 2023). "Flow cytometry analysis presented that when cocultured with si‐DHX9 glioma cells, the ratio of CD68+/CD163+ cells were significantly lower than the control; however, this effect could be partly reversed by cocultured with CSF1 overexpressed glioma cells." (PMID 36377508, 2023). "Furthermore, we randomly selected 12 glioma clinical specimens and detected some immune cell markers, including CD4, FOXP3, CD68, iNOS and CD206, to verify our bioinformatics analysis results." (PMID 37006287, 2023). "Moreover, multiple fluorescence staining showed that BCL2A1, CD68 and CCL2 were coexpressed in glioma tissues." (PMID 37889551, 2023). "Hence, we concluded that CD68+CD163+ M2 macrophages, and CD8+ T cells, were the prepotent infiltrated immune cell types in glioma." (PMID 36524115, 2022). "CD11c+CD68+CD163+ APCs were the immune population found to be preferentially enriched in gliomas relative to metastases, irrespective of the tumor compartment being considered (edge, P = 0.0311; tumor, P = 0.0003; necrosis, P = 0.0007)." (PMID 35316217, 2022). "After adjustment based on glioma purity, MS4A6A remained notably related to the majority of signatures of immune cells, particularly macrophages (GBM: CD68: ρ = 0.623, p < 0.001; LGG: CD68: ρ = 0.805, p < 0.001) and M2 macrophages (GBM: CD163: ρ = 0.591, p < 0.001; LGG: CD163: ρ = 0.750, p < 0.001)." (PMID 36119086, 2022). "In contrast, gliomas typically lacked dyad and cluster interactions, except for T cell CD68+ cell dyads within the tumor." (PMID 35316217, 2022). "We performed immunohistochemical staining of SPON2, IFI44, CD68, and CD206 in 33 cases of gliomas." (PMID 34136486, 2021). "In addition, we verified the association of SPON2 and IFI44 genes with macrophage recruitment and performed immunohistochemical staining on glioma samples for SPON2, IFI44, the macrophage marker CD68, and the M2 macrophage marker CD206." (PMID 34136486, 2021). "We also found that the M2 markers CD68 and CD163 were highly expressed in high-grade gliomas." (PMID 33898320, 2021). "The levels of the marker for the general activated microglia, CD68, markers for M1 microglia (CD86 and MHC II) and markers for M2 microglia (CD206 and CD163) were all increased in GL261-C glioma tissue than in GL261-eGFP and GL261-vC glioma tissues." (PMID 32550897, 2020). "In the gliomas, P2RY12 immunoreactivity delineated CD68 negative cells with otherwise microglial features from CD68 positive tumor associated macrophages (TAMs)." (PMID 28073370, 2017). "Moreover, the relation of SERPINA3 levels and CD68, IBA1 was explored in primary gliomas." (PMID 41550507, 2026). "Moreover, we confirmed the co-expression CD68/SERPINA3, IBA1/SERPINA3 in glioma specimens, indicating SERPINA3 may contribute to the intratumoral infiltration of GAMs." (PMID 41550507, 2026). "We performed single-cell transcriptomic analysis on the orthotopic glioma mouse model (GSE246154) from the GEO database using R. The results indicated that the Ifnar2 gene was enriched in T cells, while the CD68 and CD33 genes were less enriched in macrophages." (PMID 40297576, 2025). "Interestingly, CD3 and CD68 positive cells are observed to a higher extent only in patients with GBM and LGG, supporting the relevance of the TME together with personalized approaches in glioma." (PMID 35250490, 2022).
glioma (continued). "A large number of CD68+ cells was detected infiltrating the glioma tissue in nontreated animals." (PMID 35115369, 2022). "Interestingly, non-responder gliomas had an immunosuppressive expression signature and higher levels of CD68+ macrophage infiltration." (PMID 32823925, 2020). "The results show a significant reduction in the percentage of CD68 and CD206 (a marker of M2 protumoral macrophages) positive cells, in SVZ-vIII tumors treated with VP3.15, but not in GL261 gliomas." (PMID 40157890, 2025). "Glioma cell invasion is strongly but not significantly correlated with either astrocyte %GFAP+ (Spearman rs = −0.767, p > 0.05) or microglia %CD68+ (rs = 0.747, p > 0.05)." (PMID 35906273, 2022). "SPON2, IFI44, CD68, and CD206 were highly expressed in high-grade gliomas, and SPON2 was positively correlated with CD68 rather than CD206, whereas IFI44 was positively correlated with both CD68 and CD206 expression." (PMID 34136486, 2021). "Double staining of P2RY12 with the pan- macrophage marker CD68 revealed a large population of CD68 negative, P2RY12 positive cells (CD68- P2RY12+) distinct from TAMs (CD68+ P2RY12-) in all glioma samples." (PMID 28073370, 2017). "Although we were unable to determine the exact proportions of astrocytes, glioma cells and microglia in this study, ICC showed no immunofluorescence for the microglial markers, CD68 and CD11b, in the majority of cultures." (PMID 25415278, 2014). "In human gliomas, 30-50% of the cells are CD68+ or IBA1+ tissue macrophages; however, we previously showed that the percentage of CD68+ or IBA1+ cells in these human tumors did not correlate with glioma malignancy grade." (PMID 24147027, 2013). "Our previous studies demonstrated that the percentage of CD68+ and IBA1+ cells were increased in gliomas relative to non-neoplastic brain, with both low-grade and high-grade gliomas harboring equivalent percentages of macrophages." (PMID 24147027, 2013). "The data showed that the mRNA expression levels of CD68, CD163 and SIGLEC15 were higher in tumor tissues than in normal tissues across a broad spectrum of human cancers, including glioma." (PMID 37234161, 2023). "Although macrophages were abundant in glioma regions showing prominent SH activity, neither TAMRA-FP hotspots nor TAMRA-FP hotspot clusters originated from cells stained for the macrophage markers CD68, CD163 or CD169." (PMID 32190011, 2020). "CD68 staining is confined to M/Mφ population (as verified by co-labelling with GFP+ cells in CX3CR1+/GFP mice), being completely absent in glioma cells." (PMID 25818172, 2015).